IL1B (interleukin 1 beta)
Diseases named in the same sentence as IL1B in open-access papers (continued):
Sharing a sentence is not in itself a finding about the gene and the disease.
atherosclerosis (continued). "Interleukin 1β (IL-1β) is a proinflammatory cytokine that has been widely documented to play critical roles in nearly all stages of atherosclerosis from early plaque formation to the destabilization and rupture of advanced lesions." (PMID 34566523, 2021). "Despite recent positive outcomes in clinical trials with therapeutics for the treatment of atherosclerosis, namely those based on monoclonal antibodies against IL-1β and PCSK9, this disease remains the leading cause of death worldwide." (PMID 33855029, 2021). "In conclusion, our results suggest that circDENND1B is a ceRNA through which IL-1β mAb inhibits atherosclerosis." (PMID 33996813, 2021). "Atherosclerosis is a process which involves a milder degree of imbalance of the IL-1b/IL-1RA system than that observed in chronic inflammatory diseases such as rheumatoid arthritis, psoriasis, gout, or inflammatory bowel disease." (PMID 33801199, 2021). "IL-1β is known as a key component of proinflammatory cytokines and relates to the development and progression of many diseases (e.g., atherosclerosis, type II diabetes, rheumatoid arthritis, and neurogenerative diseases)." (PMID 34445749, 2021). "In this work, we conducted circRNA-sequencing in atherosclerotic mouse aortas for the first time and identified a novel circRNA, circDENND1B, through which IL-1β mAb inhibits atherosclerosis and promotes cholesterol efflux." (PMID 33996813, 2021). "As both IL-1α and IL-1β cytokines were found to be elevated in atherosclerotic plaques, their contribution to atherosclerosis development has been extensively investigated during the past decade." (PMID 33562334, 2021). "This is in contrast to our conventional understanding that IL-1β, a harbinger of inflammation, is generally detrimental to atherosclerosis." (PMID 33800271, 2021). "Data from both experimental and epidemiological studies confirm a significant role of IL-6 and TNF-α, and especially IL-1β cytokines, in the development of atherosclerosis." (PMID 32378144, 2021). "Here, the beneficial effect of Anagliptin against interleukin 1β (IL-1β)-induced cell senescence in vascular smooth muscle cells was studied to learn the promising therapeutic capacity of Anagliptin on atherosclerosis." (PMID 34288819, 2021). "It is implicated in atherosclerosis through inducing generation of cytokines and proteolytic enzymes, thus affecting the formation and stability of atheroma, and the anti-IL1B antibody is able to suppress the development of atherosclerosis." (PMID 34688276, 2021). "Eventually, it will reduce the levels of IL‐1β, thereby inhibiting the inflammatory response in atherosclerosis." (PMID 34312998, 2021). "Enhancing autophagy in macrophages can reduce macrophage apoptosis and IL-1β levels, thereby reducing atherosclerosis." (PMID 34930917, 2021). "IL-1β and IL-18 are two key in?ammatory factors in atherosclerosis development and are mainly regulated by the NLRP3 inflammasome." (PMID 34094640, 2021). "For these reasons, IL-1β is considered a stimulator of vascular calcification in the context of atherosclerosis." (PMID 34803503, 2021). "It has also been shown that TREM-1 apparently mediates ox-LDL-induced endothelial cell pyroptosis, a cell death process found in atherosclerosis, which is dependent on caspase-1 activation and IL-1β and IL-18 production." (PMID 33814983, 2021). "Enhanced atherosclerosis with TET2 deficiency in macrophages is mediated through increasing proinflammatory signaling, including IL-1β, IL-6, and NOD-, LRR-, and the pyrin domain-containing protein 3 (NLRP3) inflammasome complex." (PMID 34576030, 2021). "NLRP3 inflammasome activation results in the maturation and release of IL-1β, a cytokine with a fundamental role in establishing and driving the pathogenesis of atherosclerosis." (PMID 33855029, 2021). "Inflammatory cytokines, particularly IL-1β and IL-18, play varying roles in the development of atherosclerosis." (PMID 32378144, 2021).
atherosclerosis (continued). "In an atherosclerosis model, Rac2 prevented plaque calcification by suppressing macrophage IL-1β expression." (PMID 33011741, 2021). "IL-1β produced by myeloid cells is a crucial mediator of atherosclerosis progression: it acts systemically and in the plaque on bystander cells to augment expression of adhesion molecules and proliferation." (PMID 33790857, 2021). "IL-1β and IL-6 are the predominant pro-inflammatory ILs in atherosclerosis mainly by aggravating subsequent inflammatory cascades, mediating the acute-phase response, and promoting the fatty streak formation in atherogenesis." (PMID 33413490, 2021). "Uncontrolled TNFα/IL-1β signaling has been shown to contribute to numerous diseases, including RA, Crohn's disease, atherosclerosis, cancer, and autoimmune diseases." (PMID 33776573, 2021). "NETs turn on the transcription of IL-6 and pro-IL-1β genes in macrophages during the early inflammatory stages of atherosclerosis." (PMID 34827513, 2021). "We have briefly discussed the role of inflammatory signaling in atherosclerosis and the role of IL-1β in VSMCs." (PMID 33800271, 2021). "In this connection, our present study identifies PVAT as a major source for vascular IL-1β, which functions in a paracrine manner on adjacent blood vessels to foster vascular inflammation and atherosclerosis." (PMID 34878840, 2021). "This pathway ties in with both the innate and acquired immune systems as well-established modifiers of atherosclerosis initiation and progression, as well as the human findings that anti-IL-1b treatment decreased cardiovascular events in the CANTOS trial." (PMID 35052410, 2021). "Dapagliflozin also suppressed iNOS, TNF-α, IL-1β, and IL-6 mRNA expression by attenuating the NF-κB transcription factor in diet-induced atherosclerosis in rat aortic arteries." (PMID 34124273, 2021). "The activation of NLRP3 inflammasome and the subsequent release of IL-1β and IL-18 contribute to the pathogenesis of atherosclerosis and HF 141-143." (PMID 33754074, 2021). "NETs license macrophages to turn on transcriptional regulation of IL-6 and pro-IL-1β via TLR2/4 in atherosclerosis." (PMID 34250033, 2021). "Similar to IL-22, IL-1β is expressed in a variety of cell types related to the development of atherosclerosis including endothelial cells, macrophages, and VSMCs." (PMID 34388961, 2021). "IL-1β and IL-18 are produced in response to inflammasome activation and play essential roles in the initiation and progression of atherosclerosis." (PMID 33534121, 2021). "Mouse studies were used to investigate the effects of the NLRP3 inflammasome’s downstream cytokines, IL-1β, and IL-18 on atherosclerosis in the early 2000s." (PMID 32648087, 2021). "IL1B is an important pro-inflammatory cytokine, and is related to the progression of atherosclerosis." (PMID 34688276, 2021). "IL-1β can be consequently considered as both a local vascular and systemic major contributor to atherosclerosis and its complications." (PMID 35008500, 2021). "Subsequently, active caspase-1 leads to proteolytic cleavage of pro-inflammatory cytokines such as pro-IL-1β and pro-IL-18 into their mature and active forms, which are the most important cytokines involved in the progression of atherosclerosis." (PMID 32378144, 2021). "The association between IL-1β overproduction by TET2 mutation and increased atherosclerosis is supported by the results of the Canakinumab Anti-Inflammatory Thrombosis Outcomes Study (CANTOS) trial." (PMID 34576030, 2021). "In a recent study, administration of MCC950 showed downregulation of IL-1β and caspase-1 and improved vascular function and reduced atherosclerosis in ApoEKO diabetic mice." (PMID 34829831, 2021). "It was proposed to be a suitable treatment method for the prevention of atherosclerosis since it can block the NLRP3 inflammasome responsible for the production of interleukins IL-1b and IL-18." (PMID 34829992, 2021).
atherosclerosis (continued). "IL-1β plays a key role in the inflammation pathway and modulates a lot of inflammatory components of atherosclerosis." (PMID 34768851, 2021). "Recent data suggested that IL-1β that is produced in response to TNF-α by the VSMCs themselves contributes to fibrous cap formation in late-stage atherosclerosis in an ApoE−/− model." (PMID 34831028, 2021). "Impaired CMA has also been proven to increase NLRP3 inflammasome activation and secretion of IL-1β, promoting vascular inflammation and atherosclerosis." (PMID 35096837, 2021). "Macrophage‐specific deletion of autophagy proteins has been shown to lead to an increased formation of atherosclerotic lesions and secretion of IL‐1β in vivo in an ApoE‐/‐ mouse model of atherosclerosis." (PMID 34377468, 2021). "Atherosclerosis is a chronic inflammatory disease and recent study indicated that atherosclerosis‐related inflammation is mainly mediated by pro‐inflammatory cytokines (IL‐1β, IL‐6 and TNF‐α) and inflammatory signaling pathways (Gisterå & Hansson, 2017)." (PMID 34592792, 2021). "On the contrary, a gain-of-function animal study on the effects of IL-1β on atherosclerosis in pigs showed that artificial expression of IL-1β on one side of the coronary artery led to increases in the coronary stenosis and aggravation of vascular diseases." (PMID 34071276, 2021). "In another study, milk-derived tripeptides decrease proinflammatory cytokines IL-1β, IL-6 as well as SOCS3 in the abdominal aorta of ApoE-deficient mice, thus reducing atherosclerosis development." (PMID 33801489, 2021). "Activated NLRP3 results in the production of IL-1β, thereby amplifying the inflammatory cascade that promotes atherosclerosis progression and plaque destabilization." (PMID 38551014, 2021). "Caspase-1 deficiency reduces endothelial cell activation and infiltration of monocytes into intima and attenuates ox-LDL-induced VSMC pyroptosis and IL-1β processing, which all suppress the development of atherosclerosis." (PMID 35096837, 2021). "Together, these results suggest that the signature of IL-32 isoforms together with IL-18, VEGF-A, IFNβ, TRAIL and IL-1β correlate with subclinical atherosclerosis in HIV infection." (PMID 33936102, 2021). "Many stimuli relevant to atherosclerosis can activate inflammasomes and promote the processing of pro-IL-1β to its active form." (PMID 33924019, 2021). "The success of recent clinical trials targeting IL-1β firmly established anti-cytokine therapy as a new pathway in atherosclerosis therapeutics." (PMID 33924019, 2021). "Proinflammatory cytokines including TNF-α, IL-1β, IL-6 are also a mediator of atherosclerosis since they activate endothelial cells, attract monocytes, and facilitate their adhesion by up-regulating MCP-1, ICAM, VCAM." (PMID 34885795, 2021). "The importance of decreasing these inflammatory cytokines to protect against CVD is supported by data from the CANTOS study where targeting IL-1β with the canakinumab-blocking antibody induced a decrease in atherosclerosis and adverse cardiac events." (PMID 33936102, 2021). "Clinical data from atherosclerotic patients showed increased IL-1β protein and mRNA levels in endothelial cells and macrophages, with increased levels corresponding to the increased severity of atherosclerosis." (PMID 34831028, 2021). "Inflammation is a crucial mediator of atherosclerosis, and several therapeutic methods that focus on inflammatory cytokines, including interleukin-1β (IL-1β), have proven effective in preventing atherogenesis." (PMID 33996813, 2021). "Treatment with HS inhibits IL-1β levels in atherosclerotic cell experiments, slowing progress in metabolic syndrome and atherosclerosis." (PMID 33071808, 2020). "IL-1β has a pivotal role in atherosclerosis, and purinergic signaling is the main triggering way for its release." (PMID 33664731, 2020).
atherosclerosis (continued). "In murine models of CHIP driven by Tet2, NLRP3 inhibitor MCC950 reduces IL-1β and atherosclerosis, and decreases fibrosis and hypertrophy following myocardial infarction." (PMID 32748835, 2020). "Recently, intervention studies have been performed on smooth muscle cell (SMC) lineage, tracing ApoE−/− mice with advanced atherosclerosis using anti-IL-1β or IgG control antibodies." (PMID 32545788, 2020). "Individuals with increased IL1-β levels had greater chance of atherosclerosis with p-value close to significance." (PMID 31664319, 2020). "Activation of the NLR family, pyrin domain-containing 3 (NLRP3) inflammasome and subsequent interleukin (IL)-1β release induces atherosclerosis and heart failure." (PMID 32358544, 2020). "Accompanied by enhanced levels of IL-1β and IL-6, a deficiency of macrophage scavenger receptor class B type I (SR-BI) and macrophage LRP-1 increases cell death and inflammation in atherosclerosis." (PMID 32346605, 2020). "Although IL-1β appears to have a protective effect against atherosclerosis here, there are several issues that need be taken into account." (PMID 33362770, 2020). "Arglabin, a plant-derived compound, inhibited the activity of the NLRP3 inflammasome and significantly reduced the production of IL-1α, IL-1β, and IL-18, reducing the production of proinflammatory mediators to alleviate atherosclerosis." (PMID 32328119, 2020). "A different study displays that ApoE-/- mice subjected to atherosclerosis show decreased lesion sites when IL-1β is blocked." (PMID 32545788, 2020). "The studies in animal models of atherosclerosis demonstrated an increased expression of IL-1α and IL-1β mRNAs in the aortas of animals fed with cholesterol." (PMID 32587660, 2020). "These clinical drug trials suggest that only specific inhibition of IL-1β effectively reduces inflammation and progression of atherosclerosis." (PMID 32047809, 2020). "To explore the effect of fucoidan on NLRP3 inflammasome and IL-1β production in atherosclerosis, we examined the serum secretion of IL-1β using ELISA." (PMID 33505579, 2020). "These crystals can trigger inflammation through the activation of the NLRP3 inflammasome and subsequent IL-1β maturation, which have lately been a major focus of atherosclerosis research." (PMID 39649554, 2020). "The cytokines contributing to atherosclerosis can be broadly divided into proatherogenic (such as IL-1β, IL-6, TNF-α) and antiatherogenic (such as IL-10 and IL-1rA)." (PMID 32485823, 2020). "Second, it can be inferred from the earlier animal experiments on IL-1Ra that IL-1β plays a more important role in early stages of atherosclerosis, while the animal model here is in a late stage." (PMID 33362770, 2020). "IL1β has been extensively studied and was originally consider a potential therapeutic target to attenuate atherosclerosis." (PMID 33324416, 2020). "Previous studies have found that IL-1β contributes to slow progressive chronic conditions such as atherosclerosis, diabetes, osteoarthritis and acute ischemic processes, including myocardial infarction and stroke." (PMID 33569001, 2020). "First of all, the protein and mRNA levels of IL-1β in atherosclerosis patients increased significantly compared with normal subjects; the levels are also positively correlated with the severity of the disease." (PMID 33362770, 2020). "The results showed that rabbits with atherosclerosis presented higher IL-6, IL-1β, IFN-γ and TNF-α levels than those in the control group; however, ruxolitinib substantially decreased IL-6, IL-1β, IFN-γ and TNF-α contents in rabbits with atherosclerosis." (PMID 32169038, 2020). "We see an upregulation of TWIST1 expression in SMCs in response to IL-1β, which is in agreement with the model of smooth muscle de-differentiation and phenotypic switching during atherosclerosis." (PMID 31917787, 2020).
atherosclerosis (continued). "Rimonabant, a selective CB1R antagonist, inhibits the development of atherosclerosis in low-density lipoprotein (LDL) receptor–deficient mice, partially by reducing IL-1β–mediated pro-inflammatory gene expression." (PMID 33584697, 2020). "Although IL-1β is one of well-demonstrated atherosclerosis- and diabetes-stimulating cytokines, its precise role and secretion mechanism in vascular calcification complication of diabetes have not been clearly detected." (PMID 31938471, 2020). "The prominent role of IL-1β in atherosclerosis is evidenced by the results of IL-1β gene ablation in ApoE–/– mice and by neutralizing antibody therapy against IL-1β that decreased the rate of recurrent cardiovascular events, as shown in the CANTOS study." (PMID 33329050, 2020). "The receptor is also endowed with the ability to induce transcription and secretion of inflammatory cytokines such as IL-1β, IL-18 (topic 5) and IL-6 which are central in atherosclerosis." (PMID 33664731, 2020). "The most prominent representative is probably IL-1β for which there is broad evidence regarding its role in atherosclerosis (for a review see24)." (PMID 33319833, 2020). "In this study, Gomez and colleagues show that IL-1β promotes multiple beneficial changes in late-stage murine atherosclerosis, including promoting the outward remodeling, formation and maintenance of a SMC/collagen-rich fibrous cap." (PMID 32545788, 2020). "Among those two, the pro-inflammatory cytokine IL-1β emerged as a major mediator of atherosclerosis development." (PMID 39649554, 2020). "Sterile inflammation is also an important driver of atherosclerosis, and targeting the production of IL-1β has proven to be a promising approach for atherosclerosis management in humans." (PMID 32849554, 2020). "It is well known that IL-1β plays a role in many diseases related to MetS: type 2 diabetes, chronic heart failure, and atherosclerosis, however, we found slight differences in its expression between the older obese and lean Zucker rats." (PMID 32188150, 2020). "The NLRP3 inflammasome, an innate immune-signaling complex, regulates CASP1 activation and the subsequent processing of pro-IL-1β, triggers vascular wall inflammatory responses and leads to the progression of atherosclerosis." (PMID 32054994, 2020). "Inhibiting NLRP3, an activator of IL-1β, causes a reduction in the expression and release of inflammatory molecules such as VCAM-1 and ICAM-1 producing atherosclerosis resistance." (PMID 32733941, 2020). "In fact, monocytes from patients with advanced atherosclerosis and/or hypercholesterolemia are hyper-responsive and therefore produce more pro-inflammatory cytokines, such as interleukin (IL) 6, IL-1β and TNFα." (PMID 33172487, 2020). "Atherosclerosis is an inflammatory disease, and the proinflammatory cytokine IL-1β has been well studied as a therapeutic target." (PMID 32047809, 2020). "Interleukine-6 (IL-6) and IL-1β are two well-established pro-inflammatory mediators and their levels are increased during atherosclerosis progression." (PMID 39649554, 2020). "The NLRP3 inflammasome is a cytosolic protein complex consisting of the NLRP3, apoptosis-associated speck-like protein (ASC), and protease caspase-1, which can cleave pro-IL-1β into mature IL-1β, thus aggravating the inflammatory response in atherosclerosis." (PMID 33505579, 2020). "Macrophages and their secreted cytokines IL-1β and IL-6 play a significant role in promoting atherosclerosis." (PMID 32384892, 2020). "This study demonstrated that targeting IL-1β improves cardiovascular outcomes in patients with stable atherosclerosis." (PMID 31824304, 2019). "Some studies have reported that IL1B:C(-31)T and IL1RN:VNTR polymorphisms are significantly correlated with the development of CAD, and thus atherosclerosis process." (PMID 31480765, 2019).